LCN2 (lipocalin 2)
Diseases named in the same sentence as LCN2 in open-access papers (continued):
Sharing a sentence is not in itself a finding about the gene and the disease.
Stroke (continued). "Following a stroke, various cells in the central nervous system (CNS), including endothelial cells, vascular smooth muscle cells (VSMCs), glial cells, and neurons, express LCN2." (PMID 36187347, 2022). "However, the specific mechanisms that induce the overexpression of LCN2 in various cells in the central nervous system after stroke require further study." (PMID 36187347, 2022). "We further expanded the study of LCN2 into the stroke filed." (PMID 35241660, 2022). "However, other investigators have shown that neuronal LCN2 expression increased after stroke in humans, in a rat cerebral–ischemia model, and in ob/ob mice." (PMID 34844610, 2021). "The early induction of LCN2 indicated that LCN2 can be used as an early blood biomarker for stroke." (PMID 34179014, 2021). "Nevertheless, targeting LCN2 to blunt post-stroke neuroinflammation may be more advantageous than inhibiting individual cytokines and chemokines because LCN2 is likely an important upstream regulator of these mediators in the inflammatory cascade." (PMID 32872405, 2020). "However, the percentage of LCN2+ cells among PMN-MDSCs or the number of LCN2+ CD11b+Ly6GhiLy6Clow cells were significantly increased in the tumor after stroke." (PMID 32153594, 2020). "Based on these results, we hypothesized that therapeutically targeting LCN2 would reduce stroke-reperfusion injury." (PMID 32872405, 2020). "Using quantitative reverse transcription-PCR, we confirmed increased mRNA expression of LCN2 as well as anti-inflammatory cytokines-Arg1, IL-10, and decreased mRNA level of pro-inflammatory cytokines-IL-6, IL-23 in the tumor of cancer-bearing stroke mice." (PMID 32153594, 2020). "In order to validate our findings in the RNA sequencing experiment, and examine whether the mRNA level of LCN2 could be altered by stroke, RNA were extracted from tumor tissues and quantitative real-time polymerase chain reaction (RT-PCR) was performed." (PMID 32153594, 2020). "The increased LCN2 expression in the tumor of stroke mice was derived from PMN-MDSC in the tumor." (PMID 32153594, 2020). "In stroke, blood levels of LCN2 correlate with disease severity and unfavorable clinical outcome." (PMID 30871254, 2019). "The results of this study indicated a possibility that LCN2 may aggravate post-stroke neuronal damage by promoting pro-inflammatory activation of astrocytes." (PMID 31426811, 2019). "Further in vivo studies are warranted to assess how LCN2 affects neuroinflammation in stroke." (PMID 31269059, 2019). "Inhibition of LCN2 can prevent astrocytes from activated in a harmful way and reduce the neurological damage in the acute phase of stroke and improve the prognosis after stroke." (PMID 31426811, 2019). "Although cytokines are known to induce LCN2 synthesis, the identity of signaling molecules that might trigger peripheral LCN2 expression in the context of stroke has yet to be discovered." (PMID 30871254, 2019). "The in vivo findings clearly support the view that (i) LCN2 mRNA expression in the peri-infarct area occurs with a short delay of several h after the initial ischemic period and shows a maximum at 72 h post stroke and (ii) is mainly due to astrocytic LCN2 expression." (PMID 30871254, 2019). "Here, we found a continuous LCN2 increase until 72 h post stroke." (PMID 30871254, 2019). "Taken together, these results suggest that LCN2 may serve as an endogenous help-me signal to defend the cerebrovascular system after stroke." (PMID 31269059, 2019). "Furthermore, plasma levels of LCN2 were measured in patients one week after ischemic stroke and analyzed for a correlation to post-stroke infections and clinical outcome at 90 days." (PMID 27152948, 2016). "In our study, with an interval of one week from stroke onset to blood sampling, we could show that circulating LCN2 is a marker of simultaneously evolving infections and contributes to the prediction of clinical outcome." (PMID 27152948, 2016).
Stroke (continued). "Plasma levels of LCN2 measured in patients one week after ischemic stroke contribute to the prediction of clinical outcome at 90 days and reflect the systemic response to post-stroke infections." (PMID 27152948, 2016). "Although our study cohort is selected, with our exclusion criteria we intended to exclude factors other than post-stroke infections which could have an influence on circulating LCN2." (PMID 27152948, 2016). "Recently, rapidly elevated Lcn2 levels have been reported in the plasma of ischemic stroke patients, but its role in strokes is unknown." (PMID 27213359, 2016). "In human stroke patients, plasma levels of LCN2 were determined one week after ischemic stroke." (PMID 27152948, 2016). "Taken together, our results suggest that reduction of PKCδ activation and LCN2 release might prove useful in reducing post-ischemic inflammation and brain injury after stroke." (PMID 25890235, 2015). "Given our current results showing that LCN2 release is reduced in Prkcd−/− mice, the mild stroke phenotype in Prkcd−/− mice may result in part from reduced release of LCN2." (PMID 25890235, 2015). "On the basis of this mechanism, it has been suggested that LCN2 may induce neuronal apoptosis during stroke-reperfusion injury." (PMID 25702801, 2015). "After a careful literature search to study known functions of these potential substrates and evaluate their potential contribution to understanding the role of PKCδ in stroke-induced reperfusion injury, we decided to focus on LCN2, a 25 kDa protein band identified in the fraction of pI 7–10." (PMID 25890235, 2015). "Moreover, stroke patients with higher LCN2 levels in blood plasma show higher cardiovascular mortality." (PMID 25890235, 2015). "In contrast, LCN2, an iron-trafficking protein shown to be specifically induced in astrocytes following inflammation and stroke, was also induced following stab wound injury, but activation in Sema4B−/− mice was ∼1.5 times higher compared to that in Sema4B+/− mice." (PMID 26464987, 2015). "The elevated level of LCN2 after stroke may exacerbate cerebral infarction and contribute to poor neurological outcome by enhancing inflammatory cell infiltration and promoting neuronal apoptosis." (PMID 25702801, 2015). "Notably, analysis of 341 DE mRNA associated with stroke (259 upregulated, 82 downregulated) in the IR group revealed upregulation of genes like Ccl2, Cxcl1, C3, Serpine1, Adamts7, Csf3, Ptx3, MMP8, Lif, and Lcn2, and downregulation of Gdf10, Agtr2 and Shank3." (PMID 39170713, 2024). "Finally, we do not have detailed data on pre-stroke serum LCN2 and cannot establish causality based on observational data." (PMID 37543589, 2023). "LCN2 may involve in the pathophysiology of clinical worsening after stroke." (PMID 36974345, 2023). "Overall, the key significantly upregulated genes based on FC values were Cyp2a5, Tgm1, and Lcn2 (2.4, 4.57, and 4.26 folds, respectively), whereas downregulated genes were Prl, Hcrt, and Pou4f2 (−4.35, −3.3, and −6.1 folds, respectively), at pre-, post-stroke day 1 and day 3, respectively." (PMID 37175797, 2023). "Therefore, it is necessary to investigate the mechanism of LCN2 induced brain damage after stroke." (PMID 36187347, 2022). "However, the role of LCN2 as an iron regulator in stroke is still far from understood." (PMID 36187347, 2022). "Moreover, LCN-2 is involved in the pathophysiological processes of secondary injury after stroke." (PMID 35493318, 2022). "In addition, specific antibodies blocking LCN2 similarly depicted neuronal protection after stroke." (PMID 36187347, 2022). "However, the studies focus on the protective effect of LCN2 after stroke are few until now, the specific signaling pathways involved in LCN2’s beneficial effects remain unclear." (PMID 36187347, 2022). "Therefore, inhibiting LCN2 might be a promising therapeutic strategy to reduce post-stroke inflammation." (PMID 34179014, 2021).
Stroke (continued). "Since both NE and LCN2 have been shown to mediate neuroinflammation and BBB damage in stroke, reduced levels of NE and LCN2 in COX-2 deficient animals could be a potential mechanism underlying the vasculoprotective effects of COX-2 blockade in stroke." (PMID 32973660, 2020). "In addition, elevated LCN2 concentrations have been found in heart failure, coronary heart disease, and stroke, providing biological plausibility for the potential role of LCN2 as a biomarker in cardiovascular disease." (PMID 33192583, 2020). "PMN-MDSC could be the major source of the increased LCN2 in the cancer-bearing stroke mice." (PMID 32153594, 2020). "Moreover, LCN2 expression was identified in the ischemic brain of individuals post temporary experimental ischemia with higher plasma levels of LCN2 detected among patients with IS patients, leading to poor overall clinical outcomes accompanied by post-stroke infections." (PMID 31485266, 2019). "This suggests that LCN2 may be an effective molecule for post-stroke intervention." (PMID 31426811, 2019). "More recently, it has been shown that LCN2 may also act directly in stroke." (PMID 31269059, 2019). "The addition of LCN2 to the established prediction parameters significantly increased the AUC of generated ROC curves from 0.851 (model 1) to 0.935 (model 2), thereby demonstrating the value of LCN2 plasma levels measured one week after stroke for predicting clinical outcome at 90 days." (PMID 27152948, 2016). "Therefore, LCN2 inhibitors or anti-LCN2 antibodies may prove useful to reduce post-stroke inflammation and brain injury." (PMID 30542675, 2015). "In this study, we found that astrocyte-specific deletion of Nhe1 not only attenuated Lcn2 gene and protein expression in GFAP+ astrocytes but also reduced stroke-induced neurodegeneration." (PMID 35440572, 2022). "Increased evidence found that LCN2 can activate MMP9 by directly binding to MMP9, which finally destroys the integrity of BBB after stroke." (PMID 36187347, 2022). "In elucidating the cellular mechanisms, we found that stroke triggered activation of NADPH oxidase (NOX)-NF-κB signaling and ROS-mediated LCN2 expression." (PMID 35440572, 2022). "A recent transcriptome analysis after stroke shows that markers of reactive astrocytes, Lcn2, GFAP, vimentin, and Timp1, were highly expressed and contributed to inflammation (e.g., Spp1, Cd52, Lcn2, and Ifi202b)." (PMID 35743941, 2022). "Among the 18 upregulated genes identified in the RNA sequencing, lipocalin-2 (LCN2) not only exhibited high expression level, with the FPKM value of 6.68, but also was increased by 4.84 folds in the stroke mice compared to the sham mice." (PMID 32153594, 2020). "LCN2 monoclonal antibody (mAb) specifically targeted LCN2 in vitro and in vivo, attenuating the induction of LCN2 and pro-inflammatory mediators (iNOS, IL-6, CCL2, and CCL9) after stroke." (PMID 32872405, 2020). "Here we report that LCN2 was induced on the inner surface of cerebral endothelial cells, neutrophils, and astrocytes that gatekeep the blood–brain barrier (BBB) after stroke." (PMID 32872405, 2020). "Both flow cytometry and immunofluorescence suggested that ischemic stroke induced LCN2 expression in PMN-MDSC in the tumor and promoted the recruitment of PMN-MDSC into the tumor, which may underlie the increased immune suppressive microenvironment of the tumor after stroke." (PMID 32153594, 2020). "The stroke-induced MPO and LCN2 was minimally detected in the pMCAO model and significantly lower than the tMCAO model, showing that the infiltration of immune cells in pMCAO was not as pronounced as in tMCAO." (PMID 25702801, 2015). "Another study revealed that astrocytic Lcn-2 binds to the 24p3R, activating the NLRP3 inflammasome, and inducing astrocyte pyroptosis and pro-inflammatory factor release in the peri-infarct area after stroke." (PMID 38533497, 2024).
Stroke (continued). "Beta-2-microglobulin (B2M), cystatin C and lipocalin-2 (LCN-2) are established renal biomarkers, yet their roles in stroke have not been fully evaluated." (PMID 37155257, 2023). "We detected significant increase in LCN2 mRNA and protein expression in RA from wild-type stroke brains but not from Nhe1 Astro-KO stroke brains." (PMID 35440572, 2022). "The AUCs for lipocalin-2, sP-selectin, glial cell-derived neurotrophic factor (GDNF), sVCAM-1, sRAGE, MMP-7, D-dimer, MMP-1, Apolipoprotein CIII, myoglobin and BNDF were ≥0.75 in predicting stroke amongst children with TBM." (PMID 33930055, 2021). "Since MDSCs are abundant in tumor and play important roles in tumor progression, we then investigated whether LCN2 expression in M-MDSC (CD11b+Ly6GlowLy6Chi) and PMN-MDSC (CD11b+Ly6GhiLy6Clow) were changed in the tumor after stroke." (PMID 32153594, 2020). "By RNA-sequencing of the tumor tissue from cancer mice with or without stroke, we identified that the mRNA expression of LCN2 was significantly increased in the tumor after stroke." (PMID 32153594, 2020). "Since LCN2 was induced in cerebral endothelial cells and astrocytes gatekeeping the BBB after tMCAo, we assessed the effectiveness of LCN2 mAb to treat the BBB disruption after stroke." (PMID 32872405, 2020). "In order to elucidate the cellular source of the increased LCN2 in the tumor, we first performed flow cytometry of the tumor tissue from mice with or without stroke." (PMID 32153594, 2020). "We found that the LCN2 expression in these cells were not changed significantly in the tumor after stroke." (PMID 32153594, 2020). "Whereas no LCN2-positive cells were seen in sham animals, the number of LCN2-positive cells (mainly astrocytes) was significantly increased after stroke." (PMID 30871254, 2019). "A deeper dissection of LCN2 mechanisms in endothelium may lead to new directions and targets to rescue BBB integrity and dampen neuroinflammation after stroke." (PMID 31269059, 2019). "Plasma LCN2 levels did not correlate with maximum CRP levels measured one week after stroke (rS = 0.23; p = 0.12)." (PMID 27152948, 2016). "Among patients with post-stroke infections, the median plasma level of LCN2 was significantly higher as compared to patients with no infections (86.4 ng/ml vs. 43.4 ng/ml; p = 0.006)." (PMID 27152948, 2016). "Stroke injury, neurological deficits and infiltration of immune cells were markedly diminished in LCN2 null mice after tMCAO, but not after permanent MCAO (pMCAO)." (PMID 25702801, 2015). "The level of lipocalin-2 (LCN2) is elevated in the plasma of ischaemic stroke patients, but its role in stroke is unknown." (PMID 25702801, 2015). "The reduced stroke injury in LCN2 null mice observed in the tMCAO, but not in the pMCAO model, suggests that LCN2 is an essential factor mediating reperfusion injury after ischaemic stroke." (PMID 25702801, 2015). "In particular, the three DElncRNAs (CTD-2545M3.2, RP11-24N18.1, and RP11-473C18.7) and four DEGs (LCN2, LAIR2, RPS10, and HBB) that showed the most significant variations between PSA and HC samples were selected for further qPCR verification in the samples from the HC, stroke, PSA, and PSA-T groups." (PMID 40270596, 2025). "In addition, modulating LCN2 may be useful for preventing BBB disruptions and white matter atrophy that lead to neurological diseases, including stroke and dementia." (PMID 33945675, 2021). "Treatments with LCN2 mAb within a clinically relevant time window significantly attenuated the induction of LCN2 mRNA and protein, pro-inflammatory mediators (iNOS, IL-6, CCL2, CCL9), infiltration of neutrophils, BBB leakage, and cerebral infarction, and improved functional outcomes after stroke." (PMID 32872405, 2020). "The expression of LCN2 in the PMN-MDSC in the tumor were significantly increased in stroke mice compared to that in sham mice, and it may potentially serve as an immune modulatory target for the exacerbated cancer progression in cancer-related stroke." (PMID 32153594, 2020).
Stroke (continued). "Therefore, the increase in peripheral LCN2 levels at one week after stroke rather derives from newly recruited neutrophils and not from a response to the acute ischemia at the day of stroke onset." (PMID 27152948, 2016). "However, whereas in vitro data suggested a possible role for LCN2 in preserving BBB integrity, other studies clearly showed that LCN2 expression was found in cerebral endothelial cells and neutrophils in a mouse model of stroke, and its inhibition significantly reduced BBB leakage in vivo." (PMID 36034148, 2022). "Therefore, it may not be surprising that lipocalin 2(LCN2) should also contribute to stroke pathophysiology." (PMID 31269059, 2019). "Below, we reviewed the roles of LCN2, OPN and BMSCs in stroke except for OCN which has not been reported." (PMID 34179014, 2021). "In addition, we observed trends (0.05<p-value≤0.09) in increased levels of GDNF, interleukin (IL)-7, MMP-9, lipocalin-2, IL-4, sP-selectin, and myoglobin, and lower levels of CC5a, in children with TBM-related stroke compared to TBM without stroke." (PMID 33930055, 2021). "In another study, the concentrations of lipocalin-2, soluble receptor for advanced glycation end products (sRAGE) and CXCL10 were significantly higher in the CSF of children with TBM-related stroke compared to TBM without stroke." (PMID 35095865, 2021).
heart failure (78 papers, 2012 to 2025). Inability of the heart to pump blood at an adequate rate to meet tissue metabolic requirements. "Here, we reported that LCN2 was accumulated in LPS-induced cardiac tissue and contributed to heart failure, whereas LCN2 deficiency improved cardiac function." (PMID 35990970, 2022). "It has been demonstrated that increased circulating levels of lipocalin-2 are significantly associated with depression in patients with heart failure." (PMID 34093252, 2021). "Mechanistically, a recent review on cardiomyopathies discusses how LCN2 can regulate heart failure based on iron overload and iron deficiency." (PMID 27729871, 2016). "Lcn2 levels are also strongly associated with heart failure." (PMID 33530524, 2021). "LCN2 is considered an acute-phase protein, and increased LCN2 expression has been reported in different pathophysiological situations, including heart failure, kidney disease, and gut inflammation." (PMID 37746070, 2023). "In the GALLANT trial, plasma LCN2, along with B-type natriuretic peptide, is deemed as a biomarker for patients with acutely decompensated heart failure." (PMID 35990970, 2022). "Future studies need to be designed to evaluate the function of LCN2 in other types of heart failure." (PMID 35990970, 2022). "Serum LCN2, also known as neutrophil gelatinase-associated lipocalin (NGAL), increases in patients with MI and heart failure and predicts infarct mortality and adverse outcomes." (PMID 36034743, 2022). "Herein, LCN2 was highly expressed in cardiac tissue and accounted for heart failure in LPS-induced SCD mice, which dominantly originated from peripheral neutrophils." (PMID 35990970, 2022). "In addition, these strong indications of LCN2's correlation to heart disorders makes further elucidation of LCN2 role in heart failure a very interesting and crucial topic to study." (PMID 27729871, 2016).